KIAA0319 (KIAA0319)
Description:
Involved in neuronal migration during development of the cerebral neocortex. May function in a cell autonomous and a non-cell autonomous manner and play a role in appropriate adhesion between migrating neurons and radial glial fibers. May also regulate growth and differentiation of dendrites.
Synonyms: NMIG; DYLX2; DYX2
Tractability: Antibody: UniProt places it where antibodies can reach, with high confidence; its Gene Ontology location is reachable by antibodies, with high confidence; UniProt predicts a signal peptide or a membrane-spanning region. PROTAC: its protein half-life has been measured.
Gene: Protein-coding gene on chromosome 6 (24,544,104 to 24,646,191, reverse strand). Ensembl gene ENSG00000137261.
Subcellular location: Cell membrane; Early endosome membrane
Subcellular location (Human Protein Atlas): Vesicles; Predicted to be secreted
Pathways (Reactome):
Vesicle-mediated transport: Cargo recognition for clathrin-mediated endocytosis; Clathrin-mediated endocytosis
Gene Ontology:
Molecular function: protein binding
Biological process: negative regulation of axon extension; negative regulation of axon extension involved in regeneration; negative regulation of dendrite development; neuron migration; positive regulation of SMAD protein signal transduction
Cellular component: early endosome; early endosome membrane; plasma membrane; clathrin-coated endocytic vesicle membrane; cytoplasmic vesicle; endomembrane system
Genetic constraint (gnomAD): Loss-of-function variants: 61 observed, 85.21 expected, observed/expected ratio (o/e) 0.72, 90% interval 0.58 to 0.89. The upper end of that interval is the gene's LOEUF score, 0.89, which puts it in group 3 of 6, group 1 being the genes least tolerant of losing a copy. Missense variants: 1,074 observed, 1,236.5 expected, observed/expected ratio (o/e) 0.87, 90% interval 0.82 to 0.91. Synonymous variants: 441 observed, 486.42 expected, observed/expected ratio (o/e) 0.91, 90% interval 0.84 to 0.98.
Homologues: Orthologues: chimpanzee KIAA0319 (99% identical), macaque KIAA0319 (96% identical), pig KIAA0319 (85% identical), rabbit KIAA0319 (81% identical), mouse D130043K22Rik (76% identical), dog KIAA0319 (76% identical), rat Kiaa0319 (75% identical), tropical clawed frog kiaa0319 (55% identical), zebrafish kiaa0319 (42% identical), Drosophila melanogaster CG7565 (34% identical), Caenorhabditis elegans Y55F3BR.2 (14% identical), Caenorhabditis elegans C02F12.5 (3% identical), and 1 more. Paralogues in human: KIAA0319L (47% identical), SPINT1 (7% identical), LRP11 (7% identical), WFIKKN2 (6% identical), AMBP (5% identical), WFIKKN1 (5% identical), TFPI2 (4% identical), TFPI (3% identical), WFDC8 (3% identical), SPINT2 (3% identical), SPINT4 (2% identical), EPPIN (2% identical), and 1 more.
Diseases named in the same sentence as KIAA0319 in open-access papers:
KIAA0319 is named in the same sentence as 20 diseases in open-access papers, as found by Europe PMC text mining. Sharing a sentence is not in itself a finding about the gene and the disease. The quoted sentences say what the papers report.
dyslexia (61 papers, 2005 to 2025). A learning disorder characterized by an impairment in processing written words. "KIAA0319 has been identified as the main candidate dyslexia associated gene though knowledge about it is still limiting." (PMID 39544368, 2024). "Alternatively, KIAA0319 has also been found to associate with the rapid auditory processing deficit of dyslexia." (PMID 37259151, 2023). "Following its association with dyslexia in multiple genetic studies, the KIAA0319 gene has been extensively investigated in different animal models but its function in neurodevelopment remains poorly understood." (PMID 35031635, 2022). "Future studies will be needed to define the function of the specific KIAA0319 genetic variants associated with dyslexia in the genesis of specific cell lineages and brain development." (PMID 36016658, 2022). "Two other genes, TTRAP and THEM2, are part of the dyslexia risk haplotype that also contains KIAA0319 on chromosome 6p22.2 and are often included on a list of dyslexia-risk genes." (PMID 36452335, 2022). "The gene was linked to dyslexia, and its expression was shown to be reduced in individuals carrying a risk haplotype that included KIAA0319." (PMID 36452335, 2022). "The KIAA0319 genetic variants associated with reading and dyslexia in clinical studies are in the promoter region and regulate expression." (PMID 36016658, 2022). "The KIAA0319 variants associated with dyslexia are at the promoter region and thus the cell type and the temporal regulation of KIAA0319 expression is perhaps a major cause of the dyslexia." (PMID 36016658, 2022). "Again, no single-marker association reached statistical significance, but pairwise SNP interaction between rs2274305 in DCDC2 and rs4504469 in KIAA0319 showed significant association with dyslexia as well as with dyslexia plus comorbid ADHD." (PMID 34068951, 2021). "In particular, KIAA0319 variants have been found to be associated with dyslexia and reading abilities in multiple clinical and epidemiological cohorts." (PMID 30950042, 2019). "The DYX1C1, DCDC2, ROBO1, and KIAA0319 genes are known as the classical dyslexia susceptibility genes and they are supported by a number of independent replication studies (Carrion‐Castillo, Franke, & Fisher, 2013; Newbury, Monaco, & Paracchini, 2014)." (PMID 30950042, 2019). "In summary, our characterization of the KIAA0319 dyslexia susceptibility gene in zebrafish reveals a specific pattern of expression during development." (PMID 30950042, 2019). "Previously, we showed that a dyslexia‐associated allele (rs9406145) at this region affects the affinity for a transcription factor and reduce the expression of KIAA0319." (PMID 30950042, 2019). "The KIAA0319 gene is one of the most robust dyslexia susceptibility factors but its function remains poorly understood." (PMID 30950042, 2019). "KIAA0319, also associated with dyslexia, is associated with syllable discrimination, RAN and high frequency word reading but also with Numerical-Stroop." (PMID 30379906, 2018). "Our work establishes the dyslexia-associated TM neuronal protein KIAA0319 as an inhibitor of axon growth, both in embryonic and adult neurons." (PMID 28334068, 2017). "KIAA0319 is a transmembrane protein associated with dyslexia with a presumed role in neuronal migration." (PMID 28334068, 2017). "To date, this is the first work that starts to unravel the signaling pathway triggered by KIAA0319 in neurons and that establishes this dyslexia-associated TM neuronal protein as a player in axon growth and regeneration." (PMID 28334068, 2017). "Several candidate dyslexia-susceptibility genes, including KIAA0319, DYX1C1, and DCDC2, have been identified in humans." (PMID 27510895, 2017). "KIAA0319 also showed signatures of positive selection and is known to be related to dyslexia in individuals with mutations." (PMID 25635043, 2015).
dyslexia (continued). "In utero RNAi of the dyslexia-associated gene Kiaa0319 in rats (KIA-) degrades cortical responses to speech sounds and increases trial-by-trial variability in onset latency." (PMID 24871331, 2014). "KIAA0319 is the most consistently associated gene and the link between KIAA0319 and dyslexia has been replicated in many independent studies." (PMID 24871331, 2014). "In a subsequent study the late MMN was associated to rare variants between the prominent dyslexia candidate genes KIAA0319 and DCDC2, both located on chromosome 6." (PMID 22606227, 2012). "The DYX2 locus proved more complex, as it contains two candidate dyslexia susceptibility genes, KIAA0319 in the proximal portion and DCDC2 (doublecortin domain-containing protein 2; MIM 605755) approximately 200 kb distal." (PMID 23308072, 2012). "RNAi-mediated knock-down of the dyslexia-associated protein KIAA0319 disrupts radial migration; KIAA0319 is a putative adhesion protein that interacts with AP-2 and follows a CME pathway." (PMID 21445347, 2011). "Numerous genetic association studies have implicated the KIAA0319 gene on human chromosome 6p22 in dyslexia susceptibility." (PMID 19325871, 2009). "Targeted sequencing of two genes in the dyslexia-risk locus DYX2 on chromosome 6 implicate a haplotype that stretches 211kb from the downstream region of KIAA0319 to the second intron of DCDC2 and is associated with reduced performance on timed real-word reading adjusted for VIQ." (PMID 40424442, 2025). "KIAA0319 is a neuronal protein linked to dyslexia, and although its function remains unknown, it has been reported to recycle from the surface back to the Golgi region." (PMID 38552021, 2024). "Here, we tested our hypothesis that the clinical association of KIAA0319 with reading performance and dyslexia is a consequence of altered expression during early stages of neurogenesis." (PMID 36016658, 2022). "Moreover, the right temporoparietal region associated with rs1064395 in NCAN and also overlapped with a region previously associated with the dyslexia susceptibility genes KIAA0319, DYX1C1 and MRPL19, as well as CEP63." (PMID 34068951, 2021). "The genetic variants of KIAA0319 were found to be associated with dyslexia." (PMID 34680941, 2021). "Moreover, the KIAA0319 genetic associations (as with most genetic associations and with complex traits) explains only a small fraction of dyslexia heritability." (PMID 30950042, 2019). "We conducted the first zebrafish characterization of the dyslexia susceptibility KIAA0319 gene." (PMID 30950042, 2019). "We examined 4 SNPs located on genes previously associated to dyslexia (KIAA0319, DCDC2, DYX1C1 and FOXP2) and 3 SNPs within genes related to ADHD (COMT, MAOA and DBH) in a cohort of Spanish children (N = 2078) that met the criteria of having one, both or none of these disorders (dyslexia and ADHD)." (PMID 30379906, 2018). "Our results do not unveil major effects during brain development caused by removal of KIAA0319, adding evidence against the “neuronal migration” hypothesis of dyslexia." (PMID 27510895, 2017). "Amongst these, KIAA0319 emerges as a prime candidate based on consistently replicated associations in independent samples and functional evidence linking dyslexia susceptibility to transcriptional regulation of KIAA0319." (PMID 29045729, 2017). "Interestingly, KIAA0319 is located in the dyslexia susceptibility locus DYX2 (Dyslexia Susceptibility 2) that resides on chromosome 6p22 being the most consistently replicated in this disorder." (PMID 28334068, 2017). "Furthermore, targeted knock down of other dyslexia susceptibility candidate genes (such as KIAA0319 and DCDC2) resulted in similar patterns of neuronal migration." (PMID 29081827, 2017). "KIAA0319 is one of the strongest dyslexia susceptibility candidate genes identified so far, but its molecular and cellular functions are still unknown." (PMID 27510895, 2017).
dyslexia (continued). "Variants in KIAA0319 have been associated with dyslexia in at least nine independent studies." (PMID 24871331, 2014). "In view of the different languages used in Caucasian and Chinese populations, the aim of the present study was to investigate whether there is also an association of KIAA0319 in Chinese children with dyslexia and/or to the language-related cognitive skills." (PMID 25015435, 2014). "The behavioral data we collected confirmed our hypothesis that assumed in utero RNAi of the candidate-dyslexia gene Kiaa0319 in rats would cause impaired speech sound discrimination in quiet and in noise." (PMID 24871331, 2014). "In addition, RNAi downregulation of the dyslexia-susceptibility genes Dcdc2, Kiaa0319 and Dyx1c1 in rat embryos also affects neuronal migration to cortex." (PMID 22426781, 2012). "One or more of these polymorphisms might alter transcriptional regulation of KIAA0319 and thus play a role in dyslexia." (PMID 23308072, 2012). "Furthermore, the PSGs expressed in the brain and under the highest positive selection include CNTNAP4, FAN1, SNTG2, and KIAA0319, which also display high levels of expression in the cerebellum and have been associated with communication disorders, such as autism and dyslexia." (PMID 33441416, 2021). "Thus, it is reasonable to hypothesize that genes associated with dyslexia and migrational error in animal models, such as KIAA0319 and DCDC2, contribute to orbitofrontal and superior temporal sulcus findings in people with reading disability." (PMID 26835509, 2016). "The observation that variants in KIAA0319 impair speech evoked cortical activity and cause poor speech perception and reading ability is consistent with the earlier hypothesis that phonological processing is a core deficit in dyslexia." (PMID 24871331, 2014). "Our results suggest that assumed reduced expression of KIAA0319 can cause dyslexia by increasing trial-by-trial variability in auditory cortex, which could impair phoneme processing and make reading more difficult because the mapping from phonemes to graphemes is compromised." (PMID 24871331, 2014). "At the molecular level, dyslexia has been associated with genetic variations such as DCDC2, KIAA0319, and ROBO1, which affect neuronal migration and cortical layering." (PMID 40941656, 2025). "Our analysis identified the 6p22 locus previously implicated in dyslexia, childhood apraxia of speech (CAS), and language impairment, confirming the role of KIAA0319 and DCDC2 in this locus." (PMID 39202429, 2024). "DCDC2 and KIAA0319 are present on 6p22, previously reported for dyslexia and childhood apraxia of speech (CAS)." (PMID 39202429, 2024). "KIAA0319, FOXP2, and DCDC2-KIAA0319 SNPs correlated with dyslexia; DCDC2-DYX1C1 SNPs associated with ADHD; COMT1, MAOA, DBH SNPs correlated with different dysfunctions." (PMID 36970271, 2023). "Previous studies have indicated that KIAA0319 was mainly expressed in the cerebral cortex, amygdala and cerebellum, suggested the alternative level of KIAA0319 could be the cause of neuronal migration abnormalities that might lead to the development of dyslexia." (PMID 37259151, 2023). "Spatial and temporal regulation of KIAA0319 expression that are affected by the variants could affect an isolated high-order trait such as reading without global effects on brain development or cognition; children and adults with dyslexia typically have normal brain development and cognition." (PMID 36016658, 2022). "The most frequently replicated locus is DYX2 on chromosome 6p21.3, and the most frequently replicated dyslexia genes on DYX2 are KIAA0319 and DCDC2." (PMID 36016658, 2022). "The role of KIAA0319 in dyslexia remains a matter of debate, but its rapid evolution in the hominoid lineage warrants further genetic and functional studies." (PMID 33441416, 2021).
dyslexia (continued). "Briefly, more than nine loci have been identified as candidates for susceptibility to SLD, with several genes, particularly DYX1C1, ROBO1, KIAA0319, and DCDC2, repeatedly linked to the disorder and/or measures of reading processes disturbed in dyslexia." (PMID 34068951, 2021). "We also identified PSGs associated with communication disorders, such as autism (CNTNAP4, AHI1, FAN1, SNTG2, and GRIP1) and dyslexia (KIAA0319)." (PMID 33441416, 2021). "For example, certain polymorphisms in the dyslexia candidate genes DYX1C1, DCDC2, and KIAA0319 correlate with white matter density in the brain of children." (PMID 32445086, 2020). "In contrast, the combination DCDC2-KIAA0319 correlated with dyslexia independently of the inclusion/exclusion of comorbid samples." (PMID 30379906, 2018). "Previously, SNPs within three dyslexia candidate susceptibility genes (DYX1C1, DCDC2, and KIAA0319) have been shown to be associated with white matter density in the left temporoparietal region." (PMID 27240594, 2017). "Since a German group has found some interactions between DCDC2 and KIAA0319 in a large German dyslexia sample, we also attempted to find similar interactions." (PMID 29081827, 2017). "Several candidate dyslexia susceptibility genes have been identified through linkage analysis and association studies, including DYX1C1, DCDC2, and KIAA0319." (PMID 27510895, 2017). "Several dyslexia susceptibility loci and candidate genes have been identified, with DYX1C1, DCDC2, KIAA0319, and ROBO1 established as the main candidates." (PMID 29045729, 2017). "In summary, our work corroborates the importance of rs7765678-DCDC2, rs2038137-KIAA0319, and rs6935076-KIAA0319 in the aetiology of dyslexia." (PMID 27312598, 2016). "It is interesting to note that all four of the best characterized candidate-dyslexia genes (KIAA0319, ROBO1, DYX1C1, and DCDC2) interfere with auditory processing." (PMID 24871331, 2014). "Dyslexia is highly heritable and at least four candidate-dyslexia genes have been identified (KIAA0319, DYX1C1, DCDC2 and ROBO1)." (PMID 24871331, 2014). "With direct evidence implicating now DYX1C1 and DCDC2 in ciliary functions and the bioinformatic suggestion of a role for KIAA0319 as well, we propose that dyslexia should become considered as a new type of ciliopathy." (PMID 23650548, 2013). "A number of candidate dyslexia susceptibility genes have been identified, including DCDC2 and KIAA0319 on Chromosome (Chr) 6p22.2 and DYX1C1 on Chr 15q21." (PMID 23724130, 2013). "Our group has already published on candidate dyslexia genes KIAA0319, DYX1C1 and DCDC2 based on targeted genotyping of regions in a smaller dataset than is used here." (PMID 23738518, 2013). "Genetic studies in humans have led to the identification of several other candidate genes for dyslexia, among which DCDC2, KIAA0319 and ROBO1 have been strongly implicated in either neuronal migration in the developing cortex or axon and dendritic guidance." (PMID 23650548, 2013). "In the past decade, a number of candidate dyslexia susceptibility genes (CDSGs) have been identified, three of which have garnered significant support in diverse populations, including DCDC2 and KIAA0319 on Chromosome (Chr) 6p22.2 and DYX1C1 on Chr 15q21." (PMID 23724130, 2013). "Four genes associated with dyslexia in particular are involved in the development of the cerebral neocortex, either in terms of axonal guidance (ROBO1) or neuronal migration (KIAA0319, DCDC2, and DYX1C1)." (PMID 22606227, 2012). "The novel findings included a set of genes (DCDC2, DYX1C1, KIAA0319) related to a neurological disease dyslexia suggesting their potential involvement in ciliary functions." (PMID 22558177, 2012). "We analysed markers, previously reported to be associated with dyslexia, located within the MRPL19/C2ORF3, KIAA0319, DCDC2 and DYX1C1 genes in a sample of 520 individuals and tested them for association with reading and spelling measures." (PMID 20846247, 2011).